Y_RNA (Y RNA )
Gene: Miscellaneous RNA gene on chromosome 5 (150,098,406 to 150,098,506, forward strand). Ensembl gene ENSG00000199409.
Homologues: Orthologues: chimpanzee Y_RNA (100% identical). Paralogues in human: RNY3P1 (90% identical), Y_RNA (89% identical), RNY3 (88% identical), Y_RNA (88% identical), Y_RNA (87% identical), Y_RNA (86% identical), Y_RNA (85% identical), RNY3P16 (84% identical), Y_RNA (84% identical), RNY3P11 (83% identical), RNY3P14 (83% identical), Y_RNA (83% identical), and 95 more.